AR (androgen receptor)
Diseases named in the same sentence as AR in open-access papers (continued):
Sharing a sentence is not in itself a finding about the gene and the disease.
prostate carcinoma (continued). "Androgen deprivation therapy (ADT) is the longstanding treatment for advanced prostate cancer (PC) because androgen receptor (AR) is the key therapeutic vulnerability for this disease." (PMID 36453547, 2022). "Several studies observed a co-expression area of AR and NE markers in the pathological samples of prostate cancer." (PMID 36033483, 2022). "Although these studies generally focus on prostate cancer, which is mostly driven by AR signaling, these strategies, including BET inhibition can, for the same reason, also be especially effective in AR-driven TNBC." (PMID 36139513, 2022). "In the following review, we will discuss the transcription factors FOXA1, HOXB13, GATA2, ERG, and MYC as they relate to the AR cistrome and its transcriptional output during prostate cancer evolution." (PMID 36212399, 2022). "Prostate cancer is characterized by its dependency on the AR signaling and frequent activation of the Phosphoinositide 3-kinase (PI3K)/protein kinase B (AKT) signaling." (PMID 36297536, 2022). "A previous study discovered that yes-associated protein 1 (YAP1), which plays a crucial role in the mammalian hippo signaling pathway and AR, formed a protein complex in the nucleus of prostate cancer cells." (PMID 35756667, 2022). "The result was corroborated in a second validation cohort of n > 196 mixed stage patients (IST cohort), supporting an inverse relationship between CHST11 expression and AR signaling in prostate cancer." (PMID 35963852, 2022). "We have previously identified a lipid kinase phosphatidylinositol 4-phosphate 5 kinase (PIP5K1α) as an important co-factor of AR to activate transcription of AR target genes for prostate cancer cell proliferation and survival." (PMID 35386201, 2022). "Nanoparticle-based prostate cancer-specific delivery approach and adenoviral approach to systemically deliver the AR siRNA expression particles documented a rapid xenograft tumor regression and eradication owing to robust cell death in vivo." (PMID 35372068, 2022). "Another report shows that AR directly represses SNAI1 gene transcription by binding to AR-responsive elements in the SNAI1 promoter in prostate cancer, which is similar to the mechanism we present in this study for breast cancer." (PMID 35605663, 2022). "Within this context, AR signaling inhibitors are included among the agents that have been approved for the treatment of metastatic castration-resistant prostate cancer." (PMID 36010882, 2022). "This important new finding indicates inhibiting androgen receptor signaling in brain regions regulating mood generates a stronger depressogenic action than inducing very low testosterone levels with ADT in men with prostate cancer." (PMID 36418656, 2022). "Compound 2–75 is an enzalutamide hybrid with HDAC inhibitory activity that promoted p21, increased acetyl-tubulin levels (due to enhanced HDAC6 inhibition), and lowered Hsp90 and AR protein levels in C4-2 prostate cancer cells." (PMID 36034650, 2022). "Androgen receptor (AR) is expressed in 60-70% of breast cancers (BCs) and the availability of anti-AR compounds, currently used for treating prostate cancer, paves the way to tackle specifically AR-positive BC patients." (PMID 36111296, 2022). "Our results reveal that Foxp1 is a tumor suppressor in prostate cancer progression by controlling proliferation and genes regulated by the androgen receptor." (PMID 36139541, 2022). "Downregulation of ACSL4 significantly inhibits the non-AR dependent prostate cancer cells proliferation, migration and invasion." (PMID 35910359, 2022). "While it is known that AR activation promotes lipid accumulation in prostate cancer cells, intracellular lipid levels were increased even after treatment with enzalutamide, an AR signaling inhibitor." (PMID 36077824, 2022).
prostate carcinoma (continued). "AR physically interacts with β-catenin and uses β-catenin as a co-factor to amplify the transcription of AR target genes in prostate cancer, thereby competitively inhibiting TCF/LEF-mediated transcription of β-catenin target genes." (PMID 35372424, 2022). "The pioneering factor FOXA1 modulates chromatin accessibility, directly interact with AR and shapes its signalling driving prostate cancer tumor growth." (PMID 36251389, 2022). "Apparently, both non-homologous end-joining and HR DNA repair are the main effectors of AR-FL and AR-Vs in prostate cancer." (PMID 36139600, 2022). "The introduction of novel androgen receptor (AR) antagonists for clinical treatment has improved outcomes; however, most metastatic castration-resistant prostate cancer (mCRPC) patients ultimately develop resistance to these therapies." (PMID 36012492, 2022). "AR is a nuclear hormone receptor that plays a central role in prostate cancer tumorigenesis and therapy." (PMID 36459502, 2022). "Visualization of AR interactions with other proteins has been reported variously in prostate cancer cells." (PMID 37435453, 2022). "ASC-J9 induced protein degradation of the full-length AR and AR-V7 proteins via the ubiquitin-proteasome pathway in prostate cancer cells and suppressed xenograft tumor growth derived from CRPC cells." (PMID 35372068, 2022). "For example, androgen receptor (AR) belongs to the nuclear receptor superfamily and its activation is critical for prostate cancer development and progression." (PMID 35002522, 2022). "The divergent expression of hormonal receptors in human and canine prostate cancer argues against the suitability of canine prostate cancer as a model for androgen receptor signaling in human MCRPC." (PMID 35109825, 2022). "Other USP members, such as USP7, USP14, and USP22, have been found to promote cell proliferation, G0/G1 to S phase transition, and colony formation via AR in human prostate cancer cells." (PMID 35884607, 2022). "We report that high AR activity is required for growth inhibition of prostate cancer models by SPA, which occurs, in part, through downregulation of MYC." (PMID 36194476, 2022). "A further possibility is that AR signaling is bypassed or overruled by other pathways which drive proliferation or inhibit apoptosis of prostate cancer cells." (PMID 36551650, 2022). "The midline-1 (MID1) protein increased translation of the AR, and disruption of the MID1-α4/PP2A protein complex by metformin decreased AR protein levels and inhibited prostate cancer cell growth." (PMID 35327549, 2022). "At an early stage, almost all types of prostate cancer are androgen-dependent and require the AR signaling pathway for their survival." (PMID 35954292, 2022). "Preclinical studies conducted using a PTEN-deficient murine prostate cancer model and human prostate cancer xenografts showed that inhibiting both the PI3K/AKT and AR pathways had profound tumor regression compared to inhibiting a single pathway." (PMID 36297536, 2022). "Excessive activation of androgen receptors (AR) by androgen is a major factor driving the development and progression of prostate cancer." (PMID 36362304, 2022). "In summary, in this study a series of novel hydroxyazine derivatives were synthesized and evaluated for antagonistic activity against AR and cytotoxic activity against human prostate cancer cells." (PMID 36405317, 2022). "Androgen receptor signaling is critical for prostate cancer as well as normal male tissue development, thus providing a potential sex-specific discrepancy in taxane tissue toxicity." (PMID 35884386, 2022). "We further confirm the co-expression of AR and NE markers in the samples of prostate cancer with neuroendocrine differentiation from our cohort by using immunohistochemistry staining." (PMID 36033483, 2022). "Prostate cancer is a hormone-driven disease and its tumor cell growth highly relies on increased androgen receptor (AR) signaling." (PMID 35109899, 2022).
prostate carcinoma (continued). "CCAT1, as a scaffold linking DDX5 and AR transcription complex, promotes the development of castration-resistant prostate cancer." (PMID 35992805, 2022). "ZBTB46 is a novel tumorigenic factor in prostate cancer, and is negatively correlated with the AR signaling." (PMID 35633416, 2022). "RO induced apoptosis in both hormone-dependent and castration-resistant prostate cancer cells and reduced levels of androgen receptors (AR), which are pro-proliferative and vital to the development of both types of prostate cancer cells." (PMID 36582466, 2022). "Prostate cancer is the most common cancer in men and the disease is driven by the hyper-activated transcription factor, androgen receptor (AR)." (PMID 35164752, 2022). "The androgen receptor (AR) signaling axis plays a central role in prostate cancer progression and is the prime target of modern-day prostate cancer phamacopeia." (PMID 36212399, 2022). "The reliance of prostate cancer cells on androgen signaling has led to an emphasis on inhibiting AR signaling as a pharmacologic treatment, even in castration-resistant disease." (PMID 37435458, 2022). "From the multiple bulk RNA sequencing datasets, we found prostate cancer samples with simultaneously high AR and NE signature scores in all of these datasets." (PMID 36033483, 2022). "Our results revealed that the combination of tautomycin and enzalutamide inhibits prostate cancer cell proliferation by synergistically promoting AR and ARv7 protein degradation via the ubiquitin–proteasome pathway." (PMID 36446767, 2022). "The LNCaP cell line is the only androgen-dependent human prostate cancer cell line that expresses AR and PSA, which can better reflect the growth of human prostate tumor." (PMID 35168543, 2022). "This, in combination with the finding that FOXA1 is a key transcription factor in mCRPC models that rely on the AR signaling axis, posits FOXA1 as a crucial contributor to AR-dependent prostate cancer progression." (PMID 36212399, 2022). "PlexinB1 has been demonstrated to enhance resistance to androgen receptor pathway inhibition in the treatment of prostate cancer." (PMID 35794581, 2022). "Emerging strategies to therapeutically target GATA2 in prostate cancer include the GATA2 small molecule inhibitor K7174 which suppresses the expression of AR, AR splice variants, and AR target genes via a posttranscriptional mechanism of inhibition." (PMID 36212399, 2022). "In prostate cancer, in samples harboring a mutant androgen receptor (AR) gene, which are, thus, resistant to the common therapy of AR blockers, the expression levels of Cav3.3 were significantly higher compared to samples negative for AR mutation." (PMID 36077291, 2022). "Due to the highly unstable and evolving nature of prostate cancer, most patients ultimately become unresponsive even to ‘next-generation’ inhibitors of AR signaling." (PMID 35406510, 2022). "For example, glutathione S-transferase Pi 1 (GSTP1) is involved in DNA protection and androgen receptor (AR) in prostate cancer." (PMID 35069913, 2022). "Consistently, other groups also reported the co-expression of AR and NE genes in castration-resistant prostate cancer by using both molecular profiling and histological assessments." (PMID 36033483, 2022). "A strong AR suppression signaling increases visceral metastases was previously shown, although visceral metastases are rare in prostate cancer." (PMID 36289628, 2022). "Treatments based on AR expression have been studied for prostate cancer and are currently being validated in patients with TNBC." (PMID 36548336, 2022). "Other MLL1 inhibitors including MI-136 and MI-503 share a thienopyrimidine scaffolding and function via abrogation of the MLL1/Menin association to induce cell death in models of MLL1-translocated leukemias and androgen receptor–dependent prostate cancer." (PMID 36970726, 2022).
prostate carcinoma (continued). "More than a decade ago, a different prostate cancer therapeutic strategy was suggested, assuming suppression of AR function through activation of the aryl hydrocarbon receptor (AhR), i.e., an indirect approach." (PMID 36613955, 2022). "It should be noted that there are other molecular mechanisms that contribute to the development and maintenance of the AR cistrome in prostate cancer as well." (PMID 36212399, 2022). "The AR, a steroid receptor transcription factor for testosterone and dihydrotestosterone, plays an important role in the development and progression of prostate cancer and is a key therapeutic target." (PMID 35935969, 2022). "BRCA1 differentially regulates IGF-IR expression in androgen receptor (AR)-positive and AR-negative prostate cancer cells." (PMID 36010882, 2022). "The role of AR and other transcription factors on chromatin structure change and formation of condensate compartment in prostate cancer cells has only been recently investigated and appreciated." (PMID 35966880, 2022). "In the early stage, androgens and AR are required to maintain the proliferation and migration of prostate cancer cells." (PMID 36482936, 2022). "In this review, we have provided examples of how the activities of transcription factors and epigenetic and chromatin remodelers are altered, and how these, in collaboration with the AR and its cistrome, ultimately affect prostate cancer progression." (PMID 36212399, 2022). "Androgen-deprivation therapy (ADT) is often used as a first-line treatment for recurrent or metastatic prostate adenocarcinoma, a type of prostate cancer where the androgen receptor (AR) drives tumor growth." (PMID 36672609, 2022). "miR-32 is an miRNA regulated by the androgen receptor (AR), which is overexpressed in castration-resistant prostate cancer, and miR-32 can promote tumor cell growth and aggressiveness in vitro." (PMID 35223512, 2022). "This is of a particularly high interest in prostate cancer, because the supraphysiological activation of the prostate cancer-relevant transcription factor, androgen receptor, induces DNA damage in prostate cancer cells." (PMID 35164752, 2022). "This indicates that these osteoblastic cells are more susceptible to bone cell stimulation regulating proliferation, compared to the osteolytic prostate cancer cells, which display overall more dedifferentiated features such as decreased AR expression." (PMID 35971022, 2022). "FOXA1 is a critical dependency in prostate cancer cell line models, including those that transdifferentiate into AR-agnostic, neuroendocrine-like features." (PMID 35550030, 2022). "PARP-2 is a member of Poly (ADPribose) Polymerase (PARP) family which plays a critical role in AR-mediated transcription in PCa and prostate cancer progression to CRPC compared with other members." (PMID 35756667, 2022). "For example, recent studies have shown that CHIP can inhibit prostate cancer (PCa) by degrading androgen receptor (AR)." (PMID 36358773, 2022). "Prostate cancer is a hormone-dependent malignancy, whose onset and progression are closely related to the activity of the androgen receptor (AR) signaling pathway." (PMID 35864113, 2022). "Androgen receptor (AR), a ligand-dependent transcription activator, is crucial in prostate cancer development and tumor malignancy." (PMID 35159030, 2022). "This was simultaneously associated with the downregulation of oncogenic transcription factors AR and c-Myc, which highlights the therapeutic potential and clinical feasibility of this approach in prostate cancer." (PMID 35547880, 2022). "The LNCaP cells were originally derived from a lymph node metastasis of a human prostate cancer and are known to express AR." (PMID 36672609, 2022). "This AR-driven mutant was reported to have significantly enhanced viral activity in the presence of bicalutamide both in vitro and in vivo, suggesting a promising novel therapy for both prostate cancer and AR-positive TNBC patients." (PMID 35813830, 2022).
prostate carcinoma (continued). "Almost all prostate cancers express the AR (androgen receptor), which is a nuclear receptor that binds to androgens such as testosterone and dihydrotestosterone." (PMID 36358740, 2022). "During the last decade, there has been significant progress in the field of prostate cancer therapeutic treatments based on androgen receptor-axis-targeted therapies, which resulted in improved clinical outcomes [...]." (PMID 36551526, 2022). "AR is the central signal for prostate cancer progression, and CRPC development is caused by enhanced AR-mediated epigenetic control or gene induction." (PMID 36923313, 2022). "A body of evidence has additionally highlighted the implication of the AR in DDR regulation during prostate cancer progression." (PMID 35954292, 2022). "Mu and colleagues describe a JAK–STAT signaling-dependent transition to a stem-like, multilineage state that is resistant to prostate cancer AR therapy and propose combinatorial targeting of JAK–STAT proteins to resensitize resistant tumors." (PMID 36065066, 2022). "AR functions as a transcriptional activator and is involved in the progression of prostate cancer with prostate-specific antigen (PSA) being a well-established AR-induced gene." (PMID 36335093, 2022). "This study confirms the tight interconnection between AR signaling, alterations in AR expression and the transcription of DNA repair genes in clinical tumor samples and in vitro prostate cancer models." (PMID 36139600, 2022). "Here, we provide a review of the relevance of these factors in prostate cancer progression with respect to how they modify the AR cistrome." (PMID 36212399, 2022). "In the field of prostate cancer research, taxanes are known to inhibit androgen receptor (AR) signaling through microtubule dysfunction." (PMID 35884386, 2022). "Altogether, these findings suggest that triggering of TRIB2 overexpression is a fundamental mechanism in prostate cancer cells both in vitro and in vivo when treated with enzalutamide, a second-generation direct inhibitor of AR activity." (PMID 34973338, 2022). "We were therefore encouraged to evaluate a small molecule approach to target transcription and splicing of AR pre-mRNA in AR-V7-positive prostate cancer." (PMID 35087237, 2022). "Androgen receptor (AR) activation is required for promotion of prostate cancer and remains critical in the development of metastatic castration-resistant prostate cancer (mCRPC)." (PMID 37435458, 2022). "Androgen deprivation therapy suppresses the progression of hormone‐sensitive prostate cancer through the inhibition of AR signaling, although prostate cancer often acquires resistance to androgen deprivation therapy." (PMID 34057812, 2022). "These NLS genes positively correlate with conventional neuroendocrine markers such as chromogranin and synaptophysin, and negatively correlate with AR and AR target genes in advanced prostate cancer." (PMID 36159187, 2022). "Previous studies have shown that ER and PI3K/Akt signaling can drive prostate cancer growth independently of the AR, and this study targeted both by using the combination of raloxifene and RL91." (PMID 35453603, 2022). "The standard AR assay for prostate cancer is well established, but different anti-AR antibodies have been used in breast cancer." (PMID 35711833, 2022). "However, prostate cancer could overcome hormone deprivation strategies through several cellular mechanisms, such as intratumoral androgen production and the production of ligand-independent androgen receptor splice variants, known clinically as castration-resistant prostate cancer." (PMID 42040802, 2022).